INSR (insulin receptor)
Diseases named in the same sentence as INSR in open-access papers (continued):
Sharing a sentence is not in itself a finding about the gene and the disease.
Alzheimer disease (47 papers, 2007 to 2026). A progressive, neurodegenerative disease characterized by loss of function and death of nerve cells in several areas of the brain leading to loss of cognitive function such as memory and language. "Beyond Alzheimer dementia and atherosclerotic disease, SorLA also facilitates insulin receptor localization and signaling, and SorLA-deficient mice are protected from high-fat feeding, demonstrating a phenotype that is similar to that of PAI-1–/– mice." (PMID 40299646, 2025). "Brain-specific deletion of the insulin receptor in mice results in glycogen synthase kinase 2 beta activation resulting in hyperphosphorylation of tau protein, a hallmark of early Alzheimer's Disease (AD)." (PMID 28400713, 2017). "Decreased neuronal insulin receptor (IR) signaling in Alzheimer’s disease is suggested to contribute to synaptic loss and neurodegeneration." (PMID 27639375, 2016). "Accumulating evidence suggests that dysregulation of brain insulin receptor (IR) signaling is associated with the pathogenesis of Alzheimer’s disease." (PMID 27639375, 2016). "Enhanced insulin receptor signaling has been one strategy for clinical treatments for patients with Alzheimer's disease and schizophrenia, although the underlying mechanism is not clear." (PMID 20230616, 2010). "There is evidence that β-amyloid, a hallmark of Alzheimer's disease, can interfere with insulin receptor signaling, whereas insulin stimulates clearance and degradation of β-amyloid and thus prevents β-amyloid accumulation in the brain." (PMID 18215309, 2008). "Impaired insulin receptor activation in Alzheimer's disease might explain the association between diabetes and Alzheimer's disease." (PMID 29988927, 2018). "In this view, the accumulation of dysfunctional mitochondria during chronological ageing and Alzheimer’s disease (AD) is a risk factor that may contribute to the development of dysfunctional cerebral insulin receptor signalling and insulin resistance." (PMID 23730255, 2012). "Additionally, increases in brain IGF-1R and compromised insulin receptor signaling have been associated with neurodegenerative diseases such as Alzheimer’s disease." (PMID 22844398, 2012). "In general, the results of the present study support the idea that targeting insulin receptor signaling in neurons may help to reduce both cognitive deficits and neuronal dysfunctions associated with aging and Alzheimer's disease." (PMID 18215309, 2008). "Therefore, an accumulation of dysfunctional mitochondria during chronological ageing is a risk factor that contributes to the development of age-related diseases known to accompany dysfunctional cerebral insulin receptor signalling, e.g., age-associated cognitive deficits and Alzheimer’s disease." (PMID 23730255, 2012). "Alzheimer's disease, the most common brain degeneration characterized clinically by progressive decline of memory and pathologically by loss of synapses, formation of neurofibrillary tangles and neuritic plaques, has been extensively studied with respect to insulin receptor signaling." (PMID 20230616, 2010). "For instance, some notable pathways that were associated with the PD-R include neuroinflammation (immune system-related pathways), oxidative stress, metabolism (insulin receptor signaling and Type I diabetes pathways), and the Alzheimer’s disease (AD) pathway." (PMID 38982243, 2024). "Effects of insulin action towards the brain are interesting in the context of discovery, suggesting that DM can promote Alzheimer’s disease (AD) due to mechanisms including the attenuation of intracellular-insulin receptor-dependent signaling within the BBB." (PMID 37373216, 2023). "We saw little difference in insulin receptor signaling following Inceptor knockdown in neuron cultures, or in Inceptor levels with high-fat diet in mouse or Alzheimer's disease in mouse or human tissue." (PMID 37463909, 2023).
Alzheimer disease (continued). "Alzheimer’s disease (AD) is another neurodegenerative disease, which is closely correlated with the dysfunction of insulin, insulin receptors (IR), and IR signaling." (PMID 36559325, 2022). "Downregulation of INSR signaling has been implicated in several neurodegenerative diseases, particularly Alzheimer’s disease, and INSR stimulation proposed as a potential treatment for neurodegenerative disorders." (PMID 35444190, 2022). "Rapamycin is an exogenous compound that has been shown to improve cognition in Alzheimer’s disease mouse models and can regulate pathways downstream of the insulin receptor signaling pathway." (PMID 34449653, 2021). "CNS insulin levels are decreased and insulin receptor signalling is dampened in Alzheimer's disease (AD)." (PMID 32704569, 2020). "This section describes the importance of the insulin receptor in components of the BBB from research generated primarily in these knock-out mice with a focus not only on organization of the BBB but also on Alzheimer’s disease pathology and cognition." (PMID 31213970, 2019). "It has also been shown brain insulin levels and insulin receptor levels and signaling are decreased in Alzheimer’s disease." (PMID 31213970, 2019). "Neuronal specific knockout of the insulin receptor using a synapsin-1 Cre driver reduced Aβ (1–40 and 1–42) accumulation in the Tg2576 Alzheimer’s disease mouse model." (PMID 31213970, 2019). "STZ injected intracerebroventricularly (icv) to inhibit the function of the neuronal insulin receptor can induce sporadic Alzheimer disease in animal." (PMID 26060502, 2015). "Dysregulation of insulin secretion or insulin receptor signaling has also been reported in serious mental illnesses, such as Alzheimer's disease." (PMID 22348066, 2012). "Among these, Alzheimer's disease is the best-studied neurodegenerative disease with respect to insulin receptor signaling." (PMID 20230616, 2010). "Activity of choline acetyltransferase, a key enzyme of acetylcholine biosynthesis, is reduced in insulin receptor-positive neurons in Alzheimer's disease and expression of choline acetyltransferase is increased with insulin stimulation." (PMID 18215309, 2008). "Insulin receptor dysfunction can occur in Alzheimer’s disease." (PMID 39518747, 2024). "Conversely, excitation of specific signaling pathways in A2 astrocytes can improve cognitive impairment; for example, insulin therapy was shown to enhance the mental competence of patients with Alzheimer’s disease due to insulin receptor activation on A2 astrocytes." (PMID 36902058, 2023). "In addition, in the common carp liver, the KEGG pathway analysis showed that Alzheimer’s disease was related to genes INSR, GAPDHS, BAX, DHCR24, PPARG, ENO1, and VEGFA." (PMID 35741857, 2022). "As demonstrated by increased hippocampal insulin receptor density following learning in animal models and decreased insulin signaling, receptor density, and memory decline in aging and Alzheimer's diseases, numerous studies have emphasized the importance of insulin in learning and memory processes." (PMID 32852134, 2020). "At the signal transduction level, post-mortem analysis of brains from patients with Alzheimer’s disease reveals perturbed signaling downstream of the insulin receptor, including reduced insulin and IGF-1 binding to their receptors and impaired PI3K/Akt signaling." (PMID 30054579, 2018). "Accumulated evidence suggests that insulin resistance and impairments in cerebral insulin receptor signaling may contribute to age-related cognitive deficits and Alzheimer's disease." (PMID 18215309, 2008). "A large body of evidence has accumulated that impairments in cerebral insulin receptor signaling may contribute to age-related cognitive decline and Alzheimer's disease." (PMID 17919343, 2007).
Alzheimer disease (continued). "The seemingly opposite outcomes from decreased insulin receptor and IGF-1 receptor signaling implies that either they initiate different pathways or they share the same signaling pathway but bi-directionally regulate Aβ toxicity and synaptic loss in Alzheimer's disease." (PMID 20230616, 2010). "Therapeutic antibodies have been re-engineered as BSAs that target the insulin receptor, TfR, or IGFR RMT systems at the BBB for the treatment of Alzheimer’s disease and Parkinson’s disease." (PMID 37583474, 2023). "Focusing on the top three studies, the most cited article (“Defects in IGF-1 receptor, insulin receptor and IRS-1/2 in Alzheimer’s disease indicate possible resistance to IGF-1 and insulin signalling”) was published in the Neurobiology of Aging in 2010 and was cited 602 times." (PMID 41017976, 2025). "Even though insulin signaling in the CNS cannot be studied in living humans, brain slices taken post-mortem from patients with Alzheimer’s disease respond to ex vivo insulin stimulation (in terms of insulin receptor signaling phosphorylation), but not at the level of age-matched controls." (PMID 31213970, 2019).
Glucose intolerance (47 papers, 2007 to 2025). Glucose intolerance (GI) can be defined as dysglycemia that comprises both prediabetes and diabetes. "Glucose intolerance resulting from inactivation of both insulin receptor and IGF-1 receptors in the hippocampus or central amygdala caused cognitive deficits and anxiety." (PMID 36834911, 2023). "The mouse HMGA1 KO also exhibits reduced insulin receptor abundance but as part of a complex metabolic phenotype with mild glucose intolerance, hypoinsulinemia and enhanced insulin sensitivity." (PMID 28753127, 2017). "Other models of Akt suppression in the liver (i.e., deletion of hepatic insulin receptor or Akt2) also result in a reduction in TG accumulation along with glucose intolerance similar to that of the Tsc1−/− mice." (PMID 21479224, 2011). "An example of this is a mutation in the insulin receptor (insra) governing glucose intolerance in Pachón and Tinaja populations, but not Molino." (PMID 37626324, 2023). "However, the administration of fructose and/or fiber produced a decrease in liver insulin receptor, triggering glucose intolerance." (PMID 20979642, 2010). "We previously reported that the systemic inhibition of insulin receptor (IR) and IGF-1 receptor (IGF1R) by the administration of OSI-906 (linsitinib), a dual IR/IGF1R inhibitor, induced glucose intolerance, hepatic steatosis, and lipoatrophy in mice." (PMID 33105604, 2020). "Beta-cell-specific insulin receptor knock-out (BIRKO) mice showed reduced GSIS, glucose intolerance and a lower beta-cell mass, showing that at least some of the metabolic and trophic actions of autocrine-acting insulin must be mediated through the insulin receptor." (PMID 38612880, 2024). "However, this molecular mechanism cannot fully explain the metabolic alterations observed in dmpk−/− mice, especially considering the previous characterization of the muscle-insulin receptor knockout (MIRKO) mice which do not show glucose intolerance." (PMID 17987120, 2007).
Donohue syndrome (36 papers, 2011 to 2026). "Homozygous or compound heterozygous mutations to the INSR gene leads to Donohue syndrome or to its milder form—Rabson–Mendenhall syndrome." (PMID 39504571, 2025). "Donohue syndrome (also known as leprechaunism) is an extremely rare autosomal recessive disease due to mutations in the INSR gene." (PMID 38392069, 2024). "This phenotype resembles Donohue syndrome (formerly leprechaunism), caused by homozygous INSR disruptions." (PMID 38816743, 2024). "IR due to homozygous or compound heterozygous mutations localized in the α-subunit of INSR is more severe than is observed in Donohue syndrome and RMS." (PMID 38392069, 2024). "Donohue syndrome was suspected and confirmed at 8 weeks, when two heterozygous INSR stop‐gain variants, p.(Tyr94Ter) and p.(Arg1020Ter), were detected." (PMID 36398453, 2023). "Donohue syndrome is because of compound heterozygous or homozygous mutation within the insulin receptor (INSR) gene." (PMID 35178143, 2021). "Variants that affect function of the INSR gene cause Donohue syndrome, which matched the clinical suspicion in the patient." (PMID 32860008, 2021). "Homozygous and compound heterozygous mutations in INSR lead to severe IR (Donohue syndrome, Rabson-Mendenhall syndrome), whereas the heterozygous mutations in INSR cause the milder phenotype of IR syndrome." (PMID 31989990, 2020). "INSR mutations lead to heterogeneous disorders that range in severity from Donohue syndrome (leprechaunism) and Rabson-Mendenhall syndrome to the mild “type A insulin resistance syndrome”." (PMID 32018348, 2020). "Mutations in INSR lead to Donohue syndrome, a rare autosomal dominant disease that is hallmarked by low body weight, microcephaly, muscle wasting and excessive thick skin." (PMID 31101650, 2019). "Mutations in the insulin receptor (INSR) gene are responsible for Donohue syndrome (DS) and Rabson-Mendenhall syndrome (RMS)." (PMID 29082893, 2018). "Mutations in human INSR are known to cause Donohue syndrome, which is characterized by stunted growth." (PMID 27609345, 2016). "Donohue syndrome (OMIM 246200) is a genetic autosomal recessive disorder which results from the presence of homozygous or compound heterozygous mutations in the INSR (19p13.3–p13.2), that produce a total or near-total absence of functional insulin receptors." (PMID 26871809, 2016). "Other studies showed that iPSCs generated from patients carrying insulin receptor (INSR) mutations, which causes a rare form of syndromic IR or Donohue syndrome, are inadequately self-replicative and show disruption of insulin signaling events and gene expression." (PMID 35987697, 2022). "Insulin receptor (INSR) mutations lead to heterogeneous disorders that may be as severe as Donohue syndrome or as mild as “type A insulin resistance syndrome”." (PMID 32018348, 2020). "Donohue syndrome ([DS]; leprechaunism) describes a genetic autosomal recessive disorder that results from the presence of homozygous or compound heterozygous mutations in the insulin receptor gene (INSR; 19p13.3–p13.2)." (PMID 26871809, 2016). "In addition, an inactivated insulin receptor gene is associated with normal growth in mice, but mutations or deletions of the insulin receptor gene in humans with Donohue syndrome have been associated with abnormal growth, resulting in short stature." (PMID 21052545, 2011). "Pathogenic variants of the INSR gene are responsible for INSR-related severe insulin resistance syndrome (INSR-SIRS) which includes Rabson-Mendenhall syndrome (RMS) and Donohue syndrome (DS)." (PMID 40241988, 2025). "Severe insulin receptor gene (INSR)-related insulin resistance syndromes (SIR) include Donohue syndrome (DS), Rabson–Mendenhall syndrome (RMS), and type A insulin resistance." (PMID 36626508, 2022).
Donohue syndrome (continued). "Single amino acid substitutions in the insulin receptor (INSR) are the most common forms of genetic variations that account for various diseases like Donohue syndrome or Leprechaunism, Rabson-Mendenhall syndrome, and type A insulin resistance." (PMID 27840822, 2016). "For example, Donohue syndrome known as Leprechaunism is a rare and severe genetic autosomal recessive disorder due to defect in the INSR gene." (PMID 27840822, 2016). "Donohue syndrome (DS; #OMIM 246200) is a rare autosomal recessive disorder caused by homozygous or compound heterozygous mutations in insulin receptor (INSR) gene on chromosome 19p13, leading to defective insulin receptor function." (PMID 41025026, 2025). "Patients with <25% INSR function have the more severe disorders Rabson Mendenhall syndrome (RMS) and Donohue syndrome (DS; formerly “leprechaunism”)." (PMID 27856697, 2017).
hepatoma (35 papers, 2009 to 2025). "In hepatoma cells, Fen promoted ROS generation, displayed a Warburg-like effect, and enhanced insulin receptor sensitivity." (PMID 40070568, 2025). "miR-424-5p directly interacts with the 3’ UTR sequence of insulin receptor (INSR) mRNA in human hepatocellular carcinoma cell lines, thereby suppressing insulin gene expression and signaling in adipocytes." (PMID 39944642, 2025). "It has been shown previously using a broad spectrum of liver cell lines and hepatoma cells that ER-stress impairs insulin signalling by depleting the insulin receptor on the cell surface." (PMID 37020593, 2023). "Diminished Trip13 levels in hepatocellular carcinoma cells result in insulin‐receptor‐/Akt‐pathway‐dependent accumulation of lipid droplets, which act as functional acentriolar microtubule organizing centers disturbing mitotic spindle polarity." (PMID 36031387, 2022). "It is also associated with cell growth regulation in some organs, including gastric cancer, colorectal cancer, and liver carcinoma, through regulating different target genes, such as insulin receptor substrate, p85, PI3K, akt, and Crk." (PMID 27729613, 2016). "cAMP responsive element binding protein 3 (CREB3) hinders the progression of hepatocellular carcinoma (HCC) by suppressing the phosphorylation of AKT signaling through binding competitively with insulin receptor substrate 1 (IRS1) to insulin receptor (INSR)." (PMID 38952575, 2024). "Studies have shown that ALDOB-mediated fructose metabolism drives metabolic reprogramming of liver metastases from colon cancer; loss of ALDOB activates insulin receptor(IR) signaling primarily through releasing IR/ALDOB interaction to promote de novo lipogenesis and hepatocellular carcinoma." (PMID 37259038, 2023). "Notably, we found that miR-27b levels in human hepatoma cell, Huh7, influence the expression of numerous components of the insulin signaling pathways including the INSR and insulin receptor substrate 1 (IRS1)." (PMID 33212990, 2020). "To determine whether TBC1D3 modulates signal transduction through the insulin receptor, we examined insulin signaling in HepG2 cells (American Type Culture Collection, Manassas, VA), a well-studied human hepatocellular carcinoma cell line." (PMID 22348058, 2012). "Previous studies reported that silencing of GALNT2 could inhibit insulin-induced insulin receptor activation and Akt phosphorylation in hepatoma cells, whereas overexpression of GALNT2 in oral cancer cells could promote EGF-induced phosphorylation of EGFR and Akt." (PMID 32559179, 2020). "In this study, we examined the effect of RSV on insulin-induced insulin receptor (IR) phosphorylation and proteins involved in the PI3K/Akt pathway in a hepatic cell model, clone 9 (C9), and in hepatoma cells, Hepa 1-6 (H1-6)." (PMID 40806567, 2025). "■Quinoline;■Investigational for Ewing sarcoma (phase 2), colorectal carcinoma (phase 1), head and neck malignant neoplasia (phase 2), hepatocellular carcinoma (phase 2), and ovarian cancer (phase 1);■Insulin-like growth factor 1 receptor (IGF-1R) and insulin receptor inhibitor." (PMID 40298549, 2025). "Notably, we found that miR-27b controls post-transcriptional expression of numerous components of the insulin signaling pathway including the insulin receptor (INSR) and insulin receptor substrate 1 (IRS1) in human hepatoma cells." (PMID 33212990, 2020). "The insulin-mimetic ability of Cu2+ and Zn2+ to activate the PI3K/Akt pathway by the interaction with insulin-receptor (IR) and IGF1-receptor (IGF1R) in HepG2 human hepatoma cells, which result in the phosphorylation and nuclear exclusion of transcription factor FoxO1a, has been recently questioned." (PMID 28090201, 2016). "Firstly, human hepatoma HepG2 cells were exposed to varying concentrations of unsaturated (oleate) fatty acid for 18 h, but oleate did not affect the expression of INSR, IRS-1, and Akt2." (PMID 28036389, 2016).